S100A8 (S100 calcium binding protein A8)
Diseases named in the same sentence as S100A8 in open-access papers (continued):
Sharing a sentence is not in itself a finding about the gene and the disease.
tuberculosis (11 papers, 2011 to 2025). A chronic, recurrent infection caused by the bacterium Mycobacterium tuberculosis. "A major pathologic role for S100A8/A9 proteins in mediating neutrophil accumulation and inflammation associated with tuberculosis has been published." (PMID 33567747, 2021). "Previous studies have proved that S100A8/A9 proteins cause neutrophil mediated inflammation in lungs during tuberculosis pathology." (PMID 33156824, 2020). "The validation of the key biomarker S100A8 confirms its high reliability as a kinetic indicator of active tuberculosis inflammation, providing sensitive molecular tools for clinical efficacy monitoring." (PMID 41428679, 2025). "In a murine model of tuberculosis, IL-17–induced S100A8/A9 was a key factor in neutrophil accumulation and exacerbated lung inflammation by inducing proinflammatory cytokines." (PMID 25107295, 2014). "The S100A8/A9 complex is expressed in tuberculosis (TB), as S100A8/A9-expressing neutrophils are observed to assemble in granulomas and S100A8/A9 levels correlated with active disease." (PMID 34239729, 2021). "Previous studies have found that S100A8 and MIP‐1alpha (CCL3) were remarkably elevated in PE of tuberculosis patients." (PMID 40170555, 2025). "S100A8 and S100A9 are small calcium-binding proteins that are expressed in tuberculosis patients and produced by activated neutrophils and monocytes." (PMID 21249199, 2011). "Previous studies found that neutrophil recruitment was diminished in the absence of S100A8/A9 in preclinical models of invasive pneumococcal disease and tuberculosis, presumably due to a lowered CD11b expression on elicited neutrophils." (PMID 37467233, 2023). "In contrast, S100A8 expression was weak or absent in mononuclear phagocytes of sarcoidosis and tuberculosis." (PMID 33567747, 2021). "It has also been proposed that targeting S100A8/A9 proteins can decrease lung tissue damage without impacting protective immunity against tuberculosis." (PMID 33567747, 2021). "Exposure of murine peritoneal macrophages to M. tuberculosis increases SLPI secretion and accelerates both the phagocytosis and killing of the pathogen, possibly by interacting with S100A8/A9 proteins to decrease lung tissue damage without affecting protective immunity against TB." (PMID 32493477, 2020).
atopic dermatitis (10 papers, 2011 to 2025). "S100A8, S100A9, and S100A8/A9 are damage-associated molecular pattern molecules, which are highly elevated in patients suffering from atopic dermatitis and can be detected in some inflammatory reactions in activated keratinocytes." (PMID 28454097, 2017). "IL-6, S100A8, and S100A9 are three key regulators that display a positive biological relationship with atopic dermatitis and serve as major inflammatory markers under PM exposure." (PMID 35697899, 2022). "The reported list of inflammatory mediators found in atopic dermatitis includes S100A7, S100A8 S100A9, CCL2, CCL3, IL36A, IL36G, and IL36RN." (PMID 34925353, 2021). "Increased expression of the homodimeric S100A8 (A8) and S100A9 (A9) alarmins and their Calprotectin (CP) antimicrobial hetero-complex has been reported in Inflammatory Skin Diseases (ISDs) such as Atopic Dermatitis (AD), but the functional consequences of this increase are not known." (PMID 40217087, 2025).
dyslipidemia (10 papers, 2013 to 2025). "Increased gene expression of S100A8 in whole blood has been described in individuals with the metabolic syndrome and obese individuals and associated with ROS generation." (PMID 34886800, 2021). "Further research is needed to explore whether targeting S100A8 and S100A9 could mitigate dyslipidemia and reduce cardiovascular risk in patients with AD." (PMID 40191205, 2025). "In our study, AD-like model mice exhibited elevated serum S100A8 and S100A9 levels along with dyslipidemia, suggesting an interplay between inflammation and lipid metabolism." (PMID 40191205, 2025). "Studies have shown that S100A8- and S100A9-mediated inflammation can alter hepatic lipid metabolism by increasing lipogenesis and decreasing cholesterol efflux, contributing to dyslipidemia." (PMID 40191205, 2025). "Cessation of AD induction resulted in S100A8 and S100A9 downregulation and improved dyslipidemia." (PMID 40191205, 2025). "Interestingly, the present study found that S100A12 was significantly elevated in dyslipidemia PAD patients, but S100A8/A9, also as calcium-binding proteins which was reported to act an important role in oxidative stress, was not significantly elevated in these patients (p value = 0.069)." (PMID 40269701, 2025).
endothelial dysfunction (10 papers, 2011 to 2025). In vascular diseases, endothelial dysfunction is a systemic pathological state of the endothelium (the inner lining of blood vessels) and can be broadly defined as an imbalance between vasodilating and vasoconstricting substances produced by (or acting on) the endothelium. "The changes of circulating levels of S100A8/A9 were associated with endothelial dysfunction." (PMID 24595267, 2014). "Promoting the expression of adhesion molecules and facilitating the recruitment of immune system cells, S100A8/A9 exacerbates endothelial dysfunction." (PMID 40948795, 2025). "S100A8, along with its heterodimer S100A9 have been widely associated with endothelial dysfunction and even considered as a biomarker for vascular diseases." (PMID 41286097, 2025). "In ASCVD, S100A8/A9 promotes endothelial dysfunction and facilitates monocyte recruitment and foam cell formation." (PMID 40948795, 2025). "IL-35 inhibits endothelial dysfunction directly, and IL-3 upregulates S100A8 expression in HUVECs in vitro experiments." (PMID 41155408, 2025). "In addition, the S100A8/A9 complex is also involved in leukocyte recruitment, endothelial dysfunction, and oxidative stress, all of which contribute to CVD pathophysiology." (PMID 40948795, 2025). "Moreover, S100A8/A9 contributes to altered blood flow through vasoconstriction via endothelial dysfunction and enhanced platelet-leukocyte aggregates." (PMID 40948795, 2025).
glioblastoma (10 papers, 2014 to 2024). The most malignant astrocytic tumor (WHO grade IV). "The biological activity of the purified S100A8/A9 heterodimer was verified by induction of invasion of T98 cells, an aggressive glioblastoma cell line." (PMID 28955868, 2016). "Our results revealed 3 candidate biomarkers useful in glioblastoma diagnostic: CXCL4, S100A8 and S100A9, with increased serum levels/tissue overexpression in glioblastoma versus control." (PMID 25298751, 2014). "One potential limitation that may affect the utility of S100A8 as a glioblastoma marker is its overexpression in other neurological and inflammatory diseases." (PMID 34975408, 2021). "For S100A8, the average value in glioblastoma patients was 4.03 ng/mL vs 2.06 ng/mL in controls." (PMID 25298751, 2014). "The S100A8/S100A9 subtypes may be promising biomarkers for glioblastoma." (PMID 34975408, 2021). "Further studies have corroborated the presence of increased S100A8 and S100A9 levels in glioblastoma." (PMID 34975408, 2021). "However, despite showing greater expression, serum levels of S100A9 were not a sufficient prognostic measure of glioblastoma at higher transcript levels, while only S100A8 maintained a significant correlation as a marker." (PMID 34975408, 2021). "Using SELDI-ToF MS technology, a set of potential serum biomarkers for glioblastoma diagnostic was assessed, finding three proteins, chemokine CXCL4, as well as S100A8 and S100A9 proteins as putative GBM biomarkers, whose serum levels in glioblastoma were increased in comparison with controls." (PMID 32456359, 2020).
lung diseases (10 papers, 2006 to 2025). "The underlined differentially expressed proteins were further evaluated by literature search and the LRP1 and S100A8 were found to be closely correlated with lung diseases and/or glucocorticoids." (PMID 34104089, 2021). "In various lung diseases, the S100a8/S100a9 complex exacerbates inflammatory responses by activating multiple cell surface receptors and intracellular signaling pathways (including MAPK and NF-κB), thereby promoting the emission of inflammatory mediators and the recruitment of immune cells." (PMID 41044788, 2025). "From our analyses and previous literatures, we focused on Lcn2, S100a9 and S100a8 as potential genes that may play a key role in indium-induced lung diseases." (PMID 39516272, 2025). "The implication of S100A8/A9 in the inflammatory process was shown more than 20 years ago; however, its role in the pathogenesis of respiratory diseases or its usefulness as a biomarker for the appropriate diagnosis and prognosis of lung diseases have gained increasing attention in recent years." (PMID 33567747, 2021). "In human sera, S100A8 was also significantly higher in ATB compared to non-TB lung disease, LTBI, and pooled sera from normal individuals but many samples were below the limit of detection." (PMID 34403447, 2021). "Moreover, since similar elevations of S100A8/S100A9 are detected in CF patients, these results also provide justification for the application of congenic C57BL/6J CF mice as a potential model to gain insight into the pathogenesis of lung disease of CF patients and potential therapeutic avenues." (PMID 16571124, 2006).
metastatic disease (10 papers, 2009 to 2026). "A possible association of metastatic disease with S100A8/A9+ cell counts, S100A12+ cell counts, or Cal-ratios could not be evaluated due to most dogs (8/9, 89%) having suspected or confirmed metastatic disease at the time when prostatic neoplasia was diagnosed." (PMID 37946179, 2023). "The results showed that CAFs in metastatic tumors expressed high levels of KRT15, FABP4, S100A8, and COL18A1 and were associated with high enrichment of vasculature development, cell population proliferation, and epithelial cell differentiation." (PMID 36569924, 2022). "The S100A8/A9 imaging signal in the pre-metastatic lung correlated with the subsequent metastatic tumor burden in the same organ (r2=0.788; p<0.0001)." (PMID 28744322, 2017). "However, NK cells in high metastatic disease are marked by relatively lower expression of S100A8 (FDR = 1 × 10–2; a pro-inflammatory factor that promotes metastasis)." (PMID 40340807, 2025). "S100A8 and S100A9 are among the most induced immune mediators and involve in tumor-stroma paracrine crosstalk inferred by single-cell RNA-seq from metastatic tumors." (PMID 35440136, 2022). "However, macrophages in metastatic tumors had high expression of HLA-DQA2, KRT15, S100A8, and S100A9, and GO analysis showed that lipid catabolic process, myeloid leukocyte migration, and the regulation of cell activation were highly enriched." (PMID 36569924, 2022).
myocarditis (10 papers, 2021 to 2025). Myocarditis is a condition that is characterized by inflammation of the heart muscle (myocardium). "In CVB3-positive myocarditis patients, the expression of S100A8 and S100A9 in EMB specimens was associated with bad prognosis." (PMID 32440911, 2021). "Evolving evidence suggests that S100A8/A9 adds diagnostic value in all HF subtypes when combined with N-terminal pro brain natriuretic peptide (NTproBNP), but high plasma levels of this heterodimer are also elevated in myocarditis and several other inflammatory conditions." (PMID 40948795, 2025). "Patients and mice with CVB3-induced myocarditis have significantly increased levels of S100A8/S100A9, which exacerbate oxidative stress and viral replication in myocarditis, further indicating the important role of neutrophils in the antiviral immune response." (PMID 40176832, 2025). "The role of S100A8/A9 in patients with sepsis-induced cardiomyopathy and myocarditis was also studied." (PMID 40948795, 2025). "Serum S100A8/A9 levels in patients with recent-onset myocarditis have been shown to reflect inflammatory disease activity in cardiac tissue independent of viral persistence, age, or sex." (PMID 37835816, 2023). "Endomyocardial biopsies from patients with CVB3-positive myocarditis expressed a significant increase in S100A8 and S100A9 compared to healthy controls." (PMID 37175422, 2023). "Multiple studies have reported that serum S100A8/S100A9 levels derived from neutrophils were elevated in myocarditis, I/R injury, atrial fibrillation, or chronic HF, which can be used as a powerful potential biomarker." (PMID 33680285, 2021). "This suggests that S100A8/A9 may serve as a biomarker of inflammatory activity in myocarditis, reflecting the severity of the immune response." (PMID 41597048, 2025). "Additionally, S100A8/A9 was shown to play a key role in Coxsackie virus B3-induced myocarditis in both experimental and human models, and it was recognized as a tool to track disease progression." (PMID 40948795, 2025). "Increasingly, research suggests that the concentrations of S100A8/A9 proteins in the bloodstream could be pivotal prognostic markers for negative cardiovascular outcomes in patients with acute and chronic heart failure, myocarditis, and thrombosis." (PMID 39175627, 2024). "We recently demonstrated that S100A8 and S100A9 play a pivotal role in human and experimental CVB3-induced myocarditis." (PMID 34065891, 2021). "S100A8 and S100A9 have been shown to correlate with different cardiovascular diseases including myocardial infarction and myocarditis." (PMID 32440911, 2021). "Additionally, proinflammatory molecules released from monocytes and neutrophils (alarmin S100A8 and S100A9) proved to be significant predictors of myocardial damage, and the highest values in myocarditis were observed in the acute phase of the disease." (PMID 37835816, 2023). "Furthermore, there is evidence that CVB3-induced myocarditis is influenced by MDSC, which are beside neutrophils and monocytes, the main source of the pro-inflammatory alarmins S100A8 and S100A9, which mainly appear as a heterodimer S100A8/9." (PMID 34065891, 2021).
ovarian carcinoma (10 papers, 2018 to 2025). A malignant neoplasm originating from the surface ovarian epithelium. "Levels of NET protein and S100A8 have also been shown to be important markers for predicting the prognosis of patients with ovarian cancer." (PMID 36172261, 2022). "NETs proteins and S100A8/CRP ratio were up-regulated in ovarian cancer patients with favorable outcome of another recent study." (PMID 32098278, 2020). "High expression of S100a8 and S100a9 has been reported in ovarian cancer." (PMID 39796176, 2025). "Whereas, some other S100 family members, including S100A3, S100A5, S100A7, S100A7A, S100A8, S100A16 and S100G are less reported in ovarian carcinoma." (PMID 30558666, 2018). "In our research, the higher expression of S100A8 predicted favorable OS in serous, as well as grade III and stage III + IV ovarian cancer patients." (PMID 30558666, 2018). "Until now, little was known about the relationship between the S100A8/S100A9 and prognosis in ovarian cancer." (PMID 30558666, 2018). "Our results showed that S100a8 and S100a9 are highly expressed in the TME of aged animals with ovarian cancer and may contribute to a more aggressive cancer phenotype in these animals." (PMID 39796176, 2025).
uveitis (10 papers, 2016 to 2024). An inflammatory process affecting a part of or the entire uvea. "In particular, S100A8/A9 serum levels are increased constitutively in patients with HLA-B27-associated uveitis." (PMID 34783307, 2021). "S100A8/A9 serum levels in AAU patients remained at the elevated level independently of the uveitis activity." (PMID 30105034, 2018). "Compared with the IAU patients, the S100A8/A9 level was significantly higher in the AAU cohort during uveitis inactivity." (PMID 30105034, 2018). "We are confident that S100A8 has a similar function and mechanism in uveitis, but this mechanism requires further confirmation." (PMID 27786310, 2016). "We report that elevated S100A8 reflects activation of granulocytes and monocytes, and inhibition of NF-kB signaling reduces circulating blood leukocyte S100A8 expression and uveitis." (PMID 27786310, 2016). "They found the total protein concentration to be increased in the inflamed aqueous of both uveitis models, as compared to the naïve aqueous, including calprotectin (a heterodimer of S100A8 and S100A9) and apolipoprotein E. Apolipoprotein E had higher levels in EAU than PMU in the aqueous." (PMID 33343583, 2020). "This may be relevant even to human disease, as circulating S100A8/A9 were recently proposed as a biomarker of intraocular inflammation in uveitis patients." (PMID 33375578, 2020). "The vitreous also showed increased levels of S100A8 in both uveitis models, higher in PMU than EAU." (PMID 33343583, 2020). "Elevated S100A8/A9 levels and their association to disease activity have already been reported in other non-infectious uveitis entities, e.g., IAU and JIAU." (PMID 30105034, 2018). "To date, there have been few studies on S100A8 and uveitis, and the extracellular function of this protein in AAU remains unclear." (PMID 27786310, 2016). "In a pilot study on three children with JIA-uveitis, elevated levels of proteins associated with inflammatory arthritis (SEMA3G, TIMP1, HEXB, ERN1, and SAA1) was found, in addition to elevated levels of sCD14, S100A8, and SAA1, but reduced levels of S100A9, LAP3, TTR, and MIF." (PMID 34438537, 2021). "In rat models of endotoxin (lipopolisaccharide, LPS) -induced uveitis (EIU) and keratitis, S100A8-positive granulocytes and monocytes increased significantly in the iris-ciliary body and cornea as well as in the blood." (PMID 27786310, 2016). "S100A8/A9 plasma levels were significantly elevated in uveitis patients compared to non-uveitic controls." (PMID 38982370, 2024). "As elevated AqH levels of S100A8/A9 were also reported in idiopathic anterior uveitis and herpetic anterior uveitis, their presence does not appear to be specific for JIA-associated uveitis." (PMID 34438537, 2021). "S100A8/A9 heterodimers and S100A12 are elevated in both serum and AqH in JIA-associated uveitis patients as compared to JIA patients without uveitis." (PMID 34438537, 2021). "Furthermore, serum levels of both S100A8/A9 and S100A12 correlate with uveitis activity." (PMID 34438537, 2021).